RGS5 (regulator of G protein signaling 5)
Diseases named in the same sentence as RGS5 in open-access papers (continued):
Sharing a sentence is not in itself a finding about the gene and the disease.
tumor (93 papers, 2007 to 2025). "Treatment with a single OT-I adoptive transfer decreased tumor burden and significantly increased survival of Rgs5-deficient B16-OVA–bearing mice when compared with mice with WT background (P = 0.0124)." (PMID 39286984, 2024). "It has been shown that Listeria monocytogenes (Lm)-based vaccine targeting RGS5 exhibits potent anti-tumor effects by recruiting functional type-1-associated T cells and reducing tumor blood vessel rates in syngeneic mouse models of CRC." (PMID 39086395, 2024). "Cluster 0 contributed to lymphocyte regulation, cluster 1 was cCAFs (classical CAFs), involving in extracellular matrix related components and cluster 2 was tumor associated PSCs (pancreatic stellate cells), expressing marker genes such as RGS5 and ADIRF." (PMID 35733218, 2022). "Recently, RGS5 has been identified as a major gene induced in pericytes and is associated with some morphological changes in tumor vasculature." (PMID 34124063, 2021). "In this study, we found that RGS5 is closely associated with tumor invasion patterns, tumor invasion depth, and lymphatic invasion." (PMID 31049219, 2019). "Our findings are supported by previous evidence in a tumor model demonstrating that loss of RGS5 results in vascular normalization due to pericyte maturation." (PMID 31039042, 2019). "Tumor vessels of RGS5-deficient mice were characterized by reduced vessel permeability and leakage, increased structural homogeneity, improved oxygenation, and coverage by more mature pericytes." (PMID 28081641, 2017). "More specifically, reduced expression of RGS5 was associated with increased tumor aggressiveness and poor survival in keeping with our observations in NB." (PMID 23308108, 2013). "Our study is consistent with previous work that produced RGS5-deficient mice and suggested that RGS5 loss accelerated tumor development, enhanced tumor growth (in the later tumor stages), reduced survival, decreased hypoxia, and decreased vessel permeability." (PMID 22792465, 2012). "We also identify specific subtypes of stromal and immune cells critical to the formation of the pro-tumor microenvironment in metastatic lesions, including RGS5+ cancer-associated fibroblasts, CCL18+ lipid-associated macrophages, S100A8+ neutrophils and FOXP3+ regulatory T cells." (PMID 37612267, 2023). "Moreover, RGS5 deficiency has been reported to be associated with tumor progression in lung cancer, while RGS6 exerts its tumor suppressor function via G protein-independent signaling mechanisms in breast cancer." (PMID 35498542, 2022). "Interestingly, we observed a positive correlation of Tgfbi with regulator of G protein signalling 5 (Rgs5), a gene whose expression has been linked to the formation of aberrant vasculature in tumours." (PMID 33080107, 2020). "Importantly, it was also found that tumor infiltration by both endogenous and adoptively transferred lymphocytes was increased in Rgs5-deficient mice." (PMID 28066431, 2016). "On one hand, RGS5 loss results in normalization of the vasculature in vivo, which would allow penetration of T cells and chemotherapy, but otherwise RGS5 loss enhances tumor growth." (PMID 22792465, 2012). "RGS5 knockout mice showed larger tumor burden and earlier death which may be caused by pericyte maturation and vascular normalization." (PMID 21698121, 2011). "The results from TCGA_LIHC and GEO databases (GSE76427) revealed that compared with RGS5+ CAFs, substantial infiltration of TAMs and PDGFRα+ CAFs was observed in tumours." (PMID 39827226, 2025). "Next, fluorescence-activated cell sorting (FACS) was used to sort Rgs5+ CAFs, Plag2a+ CAFs and Pdgfra+ CAFs from D12 tumour tissue, and conditioned medium was collected to perform Olink detection." (PMID 39827226, 2025). "To test the effects of tubulin-binding drugs on highly proliferating pericytes, we used an in vitro model which overexpresses the Regulator of G protein signaling 5 (RGS5) that is highly upregulated in angiogenic tumor pericytes." (PMID 40140727, 2025).
tumor (continued). "Regulator of G-protein signaling 5 (RGS5)+ ECs can promote tumor lymph nodes dissemination and drug resistance by sensing oxidative stress, which provides a potential target for BC therapy." (PMID 40248695, 2025). "Expression of RGS5 in tumors is correlated with tumor growth, metastasis and poor prognosis and high RGS5 levels in tumor pericytes leads to an immunosuppressive TME42." (PMID 40585258, 2025). "We have previously shown that RGS5 is highly expressed in the tumor vasculature, most likely in pericytes." (PMID 39286984, 2024). "The overexpression of the marker gene RGS-5 and IL-6 stimulation of tumor-derived pericytes mediate CD4+ T-cell anergy in vitro, elicited by the upregulation of anergy-related factors (dgkα, erg2, and erg3)." (PMID 39086395, 2024). "This contrasts with healthy skin where APOD+ fibroblasts, RGS5+ and TAGLN+ pericytes populations largely colocalize, implying selective expansion of the RGS5+ pericytes during tumour angiogenesis." (PMID 38165934, 2024). "The RGS5+ CAFs in our study (which we appointed a T cell-exclusion role from tumor nests) also expressed MYH11, ACTA2, and COL4A1." (PMID 39516494, 2024). "Late-stage CAFs showed enrichment for Rgs5, Nfkb pathway, Serpins (a1d,a3f, e2, and i1), Timp1, Acta2 expression, and vCAF signatures, while Pdgfrb decreased with tumor progression." (PMID 38525245, 2024). "RGS5 staining showed that these cells had both stromal and perivascular tumor localization, while in adjacent normal tissue, RGS5+ cells were only near blood vessels." (PMID 38525245, 2024). "To characterize the nature of the RGS5+ cluster further, we stained tumor sections for Transgelin (TAGLN), which is a prominently expressed gene in this cluster." (PMID 39516494, 2024). "The accumulation of RGS5+fibroblasts was significantly higher in tumor tissues compared to adjacent normal tissues, highlighting the potential biological significance of RGS5+fibroblasts in the TME." (PMID 38311726, 2024). "Regulator of G protein signaling 5 (RGS5), an intracellular regulator of G protein–coupled receptors, is prominently upregulated in the angiogenic vasculature in response to tumor hypoxia." (PMID 39286984, 2024). "Immune evasion directed by RGS-5 tumor-derived pericytes has been further explored in B16F10 mass treated with a natural immunomodulator (neem leaf glycoprotein, NLGP) reported to normalize the vasculature in the TME." (PMID 39086395, 2024). "We demonstrate by in situ immunohistochemistry that RGS5+ cells are not only found in perivascular localization but are also distributed throughout the stroma in tumor regions." (PMID 39516494, 2024). "Remarkably, tumors arising in a RGS5-deficient background display vessels with normalized morphology and an overall improved blood flow, indicating that RGS5 contributes to tumor vascular remodeling." (PMID 37986113, 2023). "Clusters 4 and 5 mainly derived from tumor tissues and were designated as pericytes due to their high expression of RGS5 and KCNJ8." (PMID 37853464, 2023). "Conversely, elevated levels of RGS5 expression are demonstrated to be strongly correlated with active tumor vessel remodeling during carcinogenesis." (PMID 37986113, 2023). "Collectively, these data suggest that tumor microenvironment induces the pro-inflammatory phenotypic switching of VSMCs by tumor-derived RGS5." (PMID 37986113, 2023). "We found that the RGS5+ mCAFs subset was indeed more infiltrated in recurrent tumor patients than in primary tumor patients." (PMID 37743226, 2023). "Immunofluorescence staining showed that Flag-RGS5 derived from Lenti-RGS5-infected cancer cells was detected in α-SMA+ VSMCs after co-incubation for 48 h, indicating that the tumor-derived RGS5 was transferred into VSMCs." (PMID 37986113, 2023). "Pericyte-1 was enriched in the tumor fraction and characterized by higher expression of genes related to a pro-inflammatory capillary phenotype (RGS5, KCNJ8, AXL, ABCC9, PDGFRB, and THY1)." (PMID 36180422, 2022).
tumor (continued). "Ectopic expression of Klf4, Rgs-5, CD248 and mutant GT198 in tumor-associated pericytes can cause local and distant metastases in breast cancer and PNETs (pancreatic neuroendocrine tumors)." (PMID 35626052, 2022). "The RGS5-TGFβ-Smad2/3 axis converts pro-to anti-apoptotic signaling in tumor-residing pericytes and assists tumor growth." (PMID 36561319, 2022). "Tumor-derived PCs seem to upregulate PD-L1 expression, a negative regulator of anti-tumor T cell responses, and overexpress the PC marker RGS5, which, together with IL-6, modulates the expression of the adhesion molecule ICAM-1 and promotes T-cell anergy." (PMID 36012149, 2022). "In CT26 tumor cells group where Bcl9 was knocked down by shRNA, Rgs5, Dmkn, and Ass1 were highly expressed." (PMID 34026600, 2021). "RGS5 is found in many tissues, where it controls vascular remodeling and is responsible for abnormal tumor vascular morphology." (PMID 34748583, 2021). "We further investigated the relationship between RGS5 expression in primary tumours and the patients’ tumour status, which provide us with the state or condition of individuals’ neoplasm at the follow-up time." (PMID 32431860, 2020). "Here, by analysing the RNA seq data of primary tumours of 533 patients with RCC, we independently observed a strong association between high expression levels of RGS5 and better outcomes." (PMID 32431860, 2020). "Inevitably, there is a significant difference in RGS5 expression between female and male patients with tumours in the left kidney." (PMID 32431860, 2020). "Here, we noted a significantly higher expression level of RGS5 in primary tumours of patients with low serum calcium levels than those with normal calcium levels." (PMID 32431860, 2020). "We observed a higher level of RGS5 expression in tumour-free patients compared with patients with tumour." (PMID 32431860, 2020). "The myoepithelial structure around the mammary ducts appeared to dissolve in early tumors, with few cells expressing both αSMA and Rgs5 around the tumor islands." (PMID 31505876, 2019). "RGS5 expression has been detected in the heart, lung, skeletal muscle, and small intestine and is involved in tumor angiogenesis and gestational hypertension." (PMID 31049219, 2019). "The dominating subset of fibroblasts within the tumor stroma were cells co-expressing αSMA and Rgs5, whereas cells expressing Pdgfra and Col9 were located extratumoral and were comparatively rare." (PMID 31505876, 2019). "The regulator of G-protein signaling 5 (RGS5) is a marker of mural cells that has been identified as a key mediator of the abnormal tumor vasculature." (PMID 28081641, 2017). "A recent publication correlates RGS5 expression with increased vascular invasion, tumor recurrence, and decreased survival in patients with HCC." (PMID 25290689, 2014). "In situ hybridization at 7 days for the activated mouse (m)-pericyte marker Rgs5, a gene controlling tumor vasculature remodeling, showed the presence of m-Rgs5+-cells surrounding abnormally dilated vessels throughout the graft." (PMID 25032689, 2014). "Although very exciting, the fact that RGS5 has a dual role tumor biology (i.e., vascularization versus tumor growth) makes it unclear how modulation of RGS expression would affect therapy." (PMID 22792465, 2012). "In this study, we used Tet-off inducible expression to study the role of RGS5, in vitro and in vivo, in tumor proliferation and pathology." (PMID 22792465, 2012). "This necrosis is likely due to two factors: hypoxia resulting from aberrant tumor vasculature and RGS5 induction of apoptosis." (PMID 22792465, 2012). "Herein, we observed an increase in the survival time in mice bearing tumors with RGS5 expression coupled with increased areas of necrosis and a reduction in tumor ulceration." (PMID 22792465, 2012). "This is in agreement with the overall observations where we observed a reduced presence of tumor ulceration in mice bearing RGS5-expressing tumors." (PMID 22792465, 2012).
tumor (continued). "On the other hand, RGS5 is overexpressed in aberrant tumor vasculature, but its expression induces endothelial apoptosis, reduces cell proliferation, and increases overall survival." (PMID 22792465, 2012). "RGS5 was reported to be a key modulator of tumor pericyte maturation and play a pivotal role in tumor neovascularization." (PMID 21698121, 2011). "In addition, these pericytes are crucial to tumor neo-angiogenesis and elevated expression of RGS5 contributes to cellular survival within the TME43." (PMID 40585258, 2025). "Given the role of RGS5 in vascular remodeling and abnormal angiogenesis, expansion of VenECs may promote tumor neovascularization, facilitating tumor growth and metastatic dissemination." (PMID 41246350, 2025). "Furthermore, another research observed that RGS5+ CAFs in an epithelial ovarian subgroup supported the tumor cell metastasis with poor relapse-free survival." (PMID 39060620, 2024). "It is of higher importance that RGS5+ACTA2+ CAFs are present in all tumor samples, which might represent a general phenotype that is similar to activated fibroblasts expressing ACTA2 in non-cancerous conditions, such as wound healing." (PMID 39516494, 2024). "Since CRC progression and survival are dependent on the functionality of blood vessels that oxygenate tumor tissues and mediate metabolic processes, targeting RGS5 could potentially be a promising therapeutic approach against vascularized tumors like CRC." (PMID 39086395, 2024). "Fibroblasts from tumor adjacent skin samples are preferentially found in the healthy fibroblast and the RGS5+ cells branches, and a smaller fraction bridging to the mCAF branch, indicating that they are in a transitory position between healthy fibroblasts and CAFs." (PMID 39516494, 2024). "In tumor regions (region 1–3, and S4C, region 1-2), a positive staining for RGS5 was detected both at vessel structures and within the stroma, in comparison to the peritumoral area, where RGS5 staining was only found surrounding vessel-like structures (region 4)." (PMID 39516494, 2024). "Other tumour models crossed with the Rgs5−/− mice also generated similar findings." (PMID 33828258, 2021). "We found that the RGS5 expression level significantly decreases when the grade of tumour increases." (PMID 32431860, 2020). "Importantly, the same study indicates that the tumour endothelial cells are the main location of RGS5 in RCC." (PMID 32431860, 2020). "Importantly, we found that male patients with a primary tumour in the right kidney have a higher level of the RGS5 expression compared with the left kidney." (PMID 32431860, 2020). "We found that the grade of RCC tumours is a decreasing function of the normalized value of RGS5." (PMID 32431860, 2020). "Moreover, when we considered TNM staging system which gives us information about the size and location of the tumour, we observed a significant decrease in the RGS5 expression level when the stage increases from T1 to T3." (PMID 32431860, 2020). "However, among patients with primary tumours in the left kidney, female patients have a significantly higher RGS5 expression level." (PMID 32431860, 2020). "When looking at the localization of the main CAF subset in late tumors, which still were localized between tumor islets, one may speculate that these αSMA and Rgs5 expressing cells might have stemmed from myoepithelial cells." (PMID 31505876, 2019). "Given that RGS5 expression is high in the infiltrative type, RGS5 expression may reflect tumor invasiveness and infiltration patterns." (PMID 31049219, 2019). "We investigated the expression of the typical epithelial cell adhesion molecule N‐cadherin and E‐cadherin and mesenchymal marker vimentin to determine whether EMT occurs during tumor growth and compared the results with RGS5 expression at the same sites." (PMID 31049219, 2019).
tumor (continued). "RGS5 expression in the normal mucosa was detected in the superficial part of the tumor in the cell nucleus, whereas RGS5 expression in the invasive portion was observed in the cytoplasm, demonstrating the localized expression of RGS5 changes with tumor invasion." (PMID 31049219, 2019). "Rgs5, one of a family of molecules that inhibits signaling by G protein-coupled receptors, is expressed by pericytes and hypoxic endothelial cells and has been shown to be overexpressed in tumor vasculature." (PMID 28066431, 2016). "These observational studies provide evidence that selective RGS5 signal modulation in tumor vasculature may play a role in exacerbating not only human RCC progression, but other types of cancers." (PMID 26300785, 2015). "The correlation of increased RGS5 expression with decreased survival may reflect the level of HSC activation within the tumor, therefore predicting tumor metastasis and proliferation." (PMID 25290689, 2014). "Therefore, a potential treatment option for cancers in which the Shh signaling pathway is aberrantly activated would be to promote RGS5 expression or prolong its activity at the tumor site." (PMID 23637832, 2013). "In contrast with these studies, we created an in vivo model of tumorigenesis with inducible expression of RGS5 to measure whether there was an effect on tumor regression." (PMID 22792465, 2012). "Taken together, this data supports the idea that temporal expression and stabilization of RGS5 could be a valuable tactic within the context of a multicomponent approach for modulating tumor progression." (PMID 22792465, 2012). "Since the role of angiogenesis inhibitors is somewhat controversial (see Section 4 for more details), such a study may also clarify the extent to which RGS5 expression regulates tumor progression, perhaps via altered vascularization." (PMID 22792465, 2012). "However, our study does provide support for including RGS5 as one important component of a multicomponent approach to help modulate tumor progression." (PMID 22792465, 2012). "Interestingly, the hematoxylin and eosin stained tumor sections showed several important differences between control and RGS5-expressing tumors." (PMID 22792465, 2012). "RGS5 has also been identified as a broadly expressed tumor antigen in multiple types of cancer." (PMID 21698121, 2011). "Knockout of Rgs5 in mice promotes the maturation of pericytes and normalization of tumor vessels." (PMID 21092311, 2010). "In contrast, upregulation of Rgs5 has been reported during neovascularisation of tumours." (PMID 17986358, 2007). "Rgs5+ CAFs are RGS5 positive and characterized by high expression of collagen and EMT- associated genes, which might be associated with the production of the ECM and the formation of tumour nodular tissue." (PMID 39827226, 2025). "In addition, we were able to identify different populations of tumor capsule overexpressing cancer-associated fibroblasts (CAFs) markers such as FAP, VIM, and ACTA2 as well as hepatic stellate cells markers (HGF, LRAT, RGS5)." (PMID 37932266, 2023). "Interestingly, vCAFs shared many marker genes with pericytes, including platelet-derived growth factor receptor beta (PDGFRβ), Chondroitin Sulfate Proteoglycan 4 (CSPG4), and regulator of G protein signaling 5 (RGS5), which further supported its association with vascularization and tumor invasion." (PMID 38313431, 2023). "Moreover, iCAFs—which are more closely related to the poor prognosis of BC than mCAFs (RGS5+)—might degrade and remodel the extracellular matrix, promote the proliferation of tumour and stromal cells, and recruit immune cells to tumours." (PMID 36159866, 2022). "In addition, these tumours were less hypoxic and expressed lower levels of Rgs5." (PMID 33080107, 2020). "Importantly, when the grade of tumour increases, the RGS5 expression level significantly decreases." (PMID 32431860, 2020).